FGFR1 (fibroblast growth factor receptor 1)
Diseases named in the same sentence as FGFR1 in open-access papers (continued):
Sharing a sentence is not in itself a finding about the gene and the disease.
adenocarcinoma (35 papers, 2010 to 2025). A common cancer characterized by the presence of malignant glandular cells. "A similar increase in FGFR1 expression was observed in the EGFR-mutated NSCLC adenocarcinoma cell line PC-9 during development of erlotinib resistance (data not shown)." (PMID 28368392, 2017). "On the other hand, two FGFR1-amplified NSCLC PDX (from large cell and adenocarcinoma subtypes) with co-overexpression of FGFR1 protein responded to M6123 (selective FGFR1 antagonist)." (PMID 35402233, 2022). "A high FGFR1 protein level was reported in: Sq-NSCLCs - 16 of 171 (9%), 13 of 212 (6%), and in 22 of 267 (8.2%); adenocarcinoma histological subtype- 40 of 114 (35%), 13 of 383 (3.5%), and 40 of 309 (12.9%)." (PMID 35402233, 2022). "Although in these cases there were also higher numbers of visceral metastases, FGFR1 amplifications in brain metastases of adenocarcinomas were fivefold more frequent than in the primary tumors." (PMID 27018053, 2016). "In one transgenic mouse model, FGFR1 overexpression led to PIN, but in another model, activated FGFR1 promoted adenocarcinoma and metastasis to lymph nodes and liver." (PMID 25566502, 2014). "Our rate of 4.1% FGFR1 amplification in adenocarcinomas is similar to the rate of amplification detected in other publications." (PMID 24255716, 2013). "The rates of FGFR1 amplification using the cutoff level of 3.5 were 5.1% in squamous cell and 4.1% in adenocarcinomas." (PMID 24255716, 2013). "Their analysis included 77 adenocarcinomas, and they found FGFR1 amplification only in 1% of the patients." (PMID 24255716, 2013). "Prostate-specific activation of FGFR1 in the epithelial compartment results in epithelial-to-mesenchymal transition and development of adenocarcinoma in 100% of cases." (PMID 21952621, 2011). "In addition, H1975 is a human adenocarcinoma cell line with EGFRL858R/T790M mutation and FGFR1 expression, which can be used as an EGFR-TKI acquired resistant cell line." (PMID 31998131, 2019). "Induced activation of FGFR1 leads to invasive adenocarcinoma with 100% penetrance after a 42-week treatment with chemical inducers of dimerization, and knockout of FGFR1 in transgenic adenocarcinoma of the mouse prostate (TRAMP) models result in attenuated tumorigenesis." (PMID 38781024, 2024). "In another study using a mouse model induced with FGFR1 activation, EMT occurred in parallel with adenocarcinoma development." (PMID 33194621, 2020). "The incidence of FGFR1 amplification has been reported to be approximately 22% in LSCC, but only 3.4% in adenocarcinoma." (PMID 26936993, 2016). "In this paper, bFGF, FGFR1 and FGFR2 expression was examined in adenocarcinoma and SCC, and high bFGF expression was found to be a good predictor of OS in SCC." (PMID 26824699, 2016). "FGFR1 gene amplification was detected in 5 of 24 (21%) SCC models and c-MET gene amplification in one (14%) adenocarcinoma model." (PMID 25470237, 2015). "Increased FGFR1 expression is frequent across various lung cancer histologies, including squamous cell carcinomas (SCC) (~25%), and adenocarcinomas (~15%), and FGFR inhibitors (FGFRi) are currently being evaluated in patients with lung SCC and other malignancies." (PMID 34267282, 2021). "Interestingly, when looking up adenocarcinomas with ALK1 rearrangement, FGFR1 gene amplification correlated significantly with brain metastases." (PMID 27018053, 2016). "That no FGFR1 amplification was reported in 25 adenocarcinomas further supports the concept of marked differences in the FGFR1 amplification frequencies between these two histological subtypes." (PMID 26555375, 2015).
CNS tumors (16 papers, 2020 to 2026). "Moreover, we identified pathogenic somatic variants in the following genes associated with CNS tumors: FGFR1 (in patient 15 with LGGNT and patient 16 with DNET) and PIK3R1 (in patient 15 with LGGNT)." (PMID 39859528, 2025). "Moreover, Pem is currently under investigation in an open-label, phase II, monotherapy study (NCT05267106 – FIGHT 209) for recurrent GBM or other primary CNS tumours with an activating FGFR1-3 mutation or fusion/rearrangement." (PMID 40467542, 2025). "In this atypical lesion, we identified an FGFR1 ITD (Solid_86) which is exceedingly rare outside of CNS tumors, highlighting the expanding phenotypic spectrum to include benign lesions." (PMID 37686670, 2023). "Whereas FGFR1-IIIc was also the predominant form in other CNS tumor types as well as in our FGFR-driven control cell models, only EPN cells exhibited extensive expression of FGFR3-IIIc." (PMID 34046693, 2021). "Targeting FGFR1-related pathways may provide new treatment approaches for patients with NS and low-grade CNS tumors." (PMID 41784910, 2026). "Furthermore, ITDs in the growth factor receptors EGFR and FGFR1 are characteristic driver events described in pediatric and adult solid and central nervous system (CNS) tumors." (PMID 37686670, 2023). "The identification of the FGFR1: TACC1 fusion and methylation profiling was pivotal in achieving an accurate diagnosis, highlighting the critical role of molecular evaluation as a complement to histopathology in CNS tumor diagnostics." (PMID 40677455, 2025). "This is the case of the antitumor activity not previously reported in patients with MET and FGFR1 fusion–positive CNS tumors." (PMID 37399010, 2023). "Concerning FGFR, all cases displayed FGFR1 hotspot substitutions N546K/D (73%, 27/37) and/or K656E/M (23%, 11/37) preferentially occurring in CNS tumours, but neither FGFR1 fusion/duplication nor FGFR2/3 alterations." (PMID 38066305, 2023). "In agreement with FGFR1 alterations being promiscuously found amongst a wide spectrum of different CNS tumor types, FGFR1-altered LGNET do not form a distinct methylation cluster." (PMID 32859279, 2020). "However, our genotype–phenotype integrated diagnoses based on the 2021 WHO classification of CNS tumors were not as relevant to the genotypes as neuroimaging features; the most frequent diagnosis was MAPK pathway-altered dLGG in both BRAF V600E and FGFR1 mutations." (PMID 39081340, 2024).
infection (15 papers, 2014 to 2026). The state of being infected such as from the introduction of a foreign agent such as serum, vaccine, antigenic substance or organism. "Our results further suggest an identical pattern of alterations in the expression of these miRNAs and FGF2/FGFR1 in the lungs as a target organ system in a murine model of infection and the potential utility of these miRNAs as diagnostic biomarkers of rickettsial diseases." (PMID 30513762, 2018). "NAE1 and FGFR1 were important for infection by an early ancestral Wuhan strain as well as more recent omicron variants, indicating that neddylation and FGFR signaling are critical host processes for this coronavirus." (PMID 41585476, 2026). "In HMECs, we observed a time-dependent increase in the expression levels of both FGF2 and FGFR1, with the maximum increase at 6 h post-infection (3.06 ± 0.2- and 3.01 ± 0.5-fold, respectively, p ≤ 0.01)." (PMID 30513762, 2018). "Again, R. conorii infection dramatically downregulated both miRNAs in these tissue-specific ECs as early as 30 min post-infection in correlation with higher FGF2/FGFR1 expression." (PMID 30513762, 2018). "Infection with type II Runx2-expressing adenovirus induced Fgfr1, Fgfr2, and Fgfr3 mRNA and their IIIb and IIIc isoform mRNA." (PMID 30202094, 2018). "We next investigated the role of FGFRs in rickettsial invasion in a mouse model of infection, taking into consideration that FGFR1 is the major isoform expressed by ECs in vivo." (PMID 28806774, 2017). "In comparison to uninfected ECs, the steady-state levels of phospho-FGFR1 were significantly higher as early as 30 minutes post-infection, indicating FGFR1 activation in response to infection." (PMID 28806774, 2017). "In this study, we investigated the differential expression of four FGFR family members in A549 cells with PR8 infection and the functional roles of FGFR1 and FGFR4 on PR8 or H5N1 virus replication." (PMID 25909503, 2015). "Treatment of L. donovani-infected hamster BMDMs over 24 hrs of infection with an inhibitor of FGFR-1 resulted in a significant dose-dependent reduction of arg1 mRNA expression and parasite burden without affecting cell viability." (PMID 24967908, 2014). "The screen revealed NAE1 and FGFR1 as key contributors to infection." (PMID 41585476, 2026). "During the early stages of infection, FGFR1 could inhibit viral internalization steps, which may account for the suppressive effect of FGFR1 on virus replication." (PMID 25909503, 2015). "In addition, truncated forms of FGFR1 have been demonstrated to freely circulate in the blood, lending support to the possibility of its involvement in the systemic dissemination of rickettsiae during infection of the mammalian hosts." (PMID 30513762, 2018). "These are involved in smooth-muscle function (FGFR1, GATA5 and STIM1), tissue organization (ADAMTS10), alveolar and epithelial function (ABCA3 and CLDN18), and inflammation and immune response to infection (CFH, CYTL1, HMCN1, LRBA and STIM1)." (PMID 36914875, 2023). "Inhibition of FGFR-1 and IGF-1R decreased arg1 expression and restricted L. donovani replication in both in vitro and ex vivo models of infection." (PMID 24967908, 2014). "However by day 14 post challenge infection, CXCL2 was abundantly expressed, particularly at the lesion edge where it co-localized with FGFR1 expressing MF and F4/80 expressing MΦ." (PMID 25806513, 2015). "Additionally, PA infection affects the mRNA levels of certain subtype-specific FGFRs—namely, FGFR1, 2 and 3, but not FGFR4—although FGFR inhibition did not affect PA-mediated inflammation." (PMID 37763754, 2023). "Chemical inhibition of signaling through the fibroblast growth factor receptor-1 (FGFR-1) or insulin-like growth factor-1 receptor (IGF-IR), or genetic knockdown of STAT6 led to reduced expression of arginase and enhanced control of the infection by macrophages." (PMID 24967908, 2014).
infection (continued). "Analysis of luciferase reporter expression in the absence of GPC-N114 at 6 h postinfection (i.e., within a single replication cycle) showed that knockout of ADAM9 and PTPN11, but not FGFR1, significantly inhibited EMCV infection." (PMID 31409686, 2019).
hematologic malignancies (14 papers, 2012 to 2026). "Our work highlights the importance of sequencing based, mutation-specific therapies for FGFR1 induced hematologic malignancies." (PMID 35574218, 2022). "Ponatinib, a potent multi-target inhibitor of Abl, PDGFR, VEGFR2, FGFR1, and Src, has been used in patients with hematological malignancies." (PMID 35207746, 2022). "In addition, interleukin receptor-associated kinase 1 induces MDSCs through regulated IFN-γ signaling to promote immune escape in fibroblast growth factor receptor-1 (FGFR1)-driven hematologic malignancies." (PMID 38609997, 2024). "Conversely, FGFR1 abnormalities have been well documented in hematologic malignancies." (PMID 36551764, 2022). "In hematological malignancies, MYO18A has been found as fusions with FGFR1, PDGFRB, and MLL in other hematopoietic malignancies." (PMID 30559310, 2018).
genetic disorder (7 papers, 2012 to 2025). "Nevertheless, we can infer hypothesis on the timing from patients with genetic disorders caused by germline and mosaic forms of FGFR1 variants, which indicate that both scenarios (“secondary” hits appearing first as in familial DNETs, or hotspots appearing first as in ECCL) are possible." (PMID 41174249, 2025).
neurological diseases (7 papers, 2013 to 2025). "Four of these genes have already been implicated in a neurological disease (TMEM67, FGFR1, FRAS1 and EXOSC8), but most variants affect genes that have not previously been connected to human disease phenotypes." (PMID 27457812, 2017). "This novel FGFR1 function can be used for devising and implementing regenerative therapeutic interventions for diverse neurological diseases." (PMID 23874817, 2013). "To conclude, our study indicates that activating both TrkB and FGFR1 signalling could be a promising avenue for therapeutic interventions in neurological diseases, and chrysin appears to be a potential candidate for the development of such treatments." (PMID 39331585, 2025). "Together, our findings indicate that activating both TrkB and FGFR1 signalling could be a promising avenue for therapeutic interventions in neurological diseases, and chrysin appears to be a potential candidate for the development of such treatments." (PMID 39331585, 2025).
prostate (7 papers, 2011 to 2023). "MicroRNA-214 was identified as a negative regulator of colorectal liver metastases by regulating fibroblast growth factor receptor 1 (FGFR1) expression." (PMID 27391432, 2016).
skeletal dysplasia (7 papers, 2007 to 2025). Any Mendelian diseases that affects growth and development of the skeleton. "Even though the transplants were decalcified and, therefore, did not allow us to determine the mineralization of the newly formed bone within the ossicles, our datasets clearly indicated that the Fgfr1+/N330I variant leads to skeletal dysplasia and impaired bone metabolism." (PMID 41473314, 2025). "The described FGFR1 and FGFR2 mutations occur outside the kinase domain, but in identical positions to activating germline mutations known to predispose to skeletal dysplasias." (PMID 17487277, 2007).
hematopoietic neoplasm (6 papers, 2012 to 2025). "Myeloid and lymphoid neoplasms with aberrant FGFR1 activities have been classified into a distinct disease group in haematological neoplasms by the World Health Organization in 2008." (PMID 34732230, 2021). "To date, more than 14 FGFR1 fusion partners in hematopoietic neoplasm have been described, and the zinc-finger domain ZNF198 (also known as ZMYM2) on chromosome 13q12 is the most typical partner gene." (PMID 34732230, 2021). "Based on these criteria, hematopoietic neoplasms producing eosinophilia are initially classified according to the presence or absence of certain gene variants, including abnormalities (mutant forms) of PDGFRA, PDGFRB, or FGFR1, or the PCM1-JAK2 fusion gene." (PMID 34052871, 2021). "For example, most (chronic) hematopoietic neoplasms exhibiting the FIP1L1-PDGFRA fusion protein are responsive to treatment with imatinib whereas this is not the case in patients with a FGFR1-mutated malignancy." (PMID 34052871, 2021).
metabolic disorders (5 papers, 2013 to 2025). "Dysregulation of FGFR1 signaling has been linked to oncogenesis, developmental anomalies, and metabolic disorders, positioning FGFR1 as both a biomarker and a key therapeutic target." (PMID 41226200, 2025). "Taken together, FGFR1 functions as a central regulator of both metabolic and proliferative signaling, and its pharmacological modulation by both agonists and antagonists highlights its broad translational potential in oncology and metabolic disease therapy." (PMID 41226200, 2025). "Beyond regulating metabolic disorders in T2D, FGF21 may also directly act on the heart to ameliorate DCM, as FGFR1 and KLB—the receptor and co-receptor mediating the biological functions of FGF21—are expressed in cardiac tissue)." (PMID 40724827, 2025). "In contrast to IL-22-Fc, anti-FGFR1 antibody failed to stimulate the wound healing process in db/db mice despite lowering serum glucose, suggesting that improvement of metabolic disorders alone is not sufficient to promote wound healing in this model." (PMID 28125663, 2017). "Thus, tissue specific modulation of FGFR1 is likely necessary for therapeutic intervention for metabolic diseases or psychiatric disorders, to gain efficacy without adverse side effects related to the FGF23-axis." (PMID 23451204, 2013).
cardiovascular diseases (4 papers, 2021 to 2024). "At the same time, some studies have found that Klotho, FGFR1, and FGFR3 are expressed in the vascular wall, which suggests that the vascular wall is the target organ of FGF23, and also that FGF23 is involved in the occurrence and development of cardiovascular diseases." (PMID 39096857, 2024).
FGFR1 also shares sentences with these, for which no sentence is quoted: Anosmia (27 papers); myeloproliferative neoplasm (21); gastrointestinal stromal tumor (9); pancreatic ductal adenocarcinoma (6); Alzheimer disease (5); craniosynostosis syndromes (5); brain cancer (4); osteomalacia (4); B-cell lymphomas (3); chronic myelomonocytic leukemia (3); ductal carcinoma in situ (3); ischemic stroke (3); leiomyosarcoma (3); lung large cell carcinoma (3); lymphoblastic lymphoma (3); metastatic melanoma (3); Parkinson disease (3); primary myelofibrosis (3); stomach cancer (3); T-cell acute lymphoblastic leukemia (3); T-cell lymphoma (3); atypical teratoid rhabdoid tumor (2); bladder urothelial carcinomas (2); chordoma (2); clear cell renal cell carcinoma (2); congenital spherocytosis (2); cutaneous melanoma (2); developmental delay (2); Ectrodactyly (2); Hearing impairment (2).
A further 170 diseases each share a sentence with FGFR1 in 2 papers or fewer.